STAT3 (signal transducer and activator of transcription 3)
Diseases named in the same sentence as STAT3 in open-access papers (continued):
Sharing a sentence is not in itself a finding about the gene and the disease.
asthma (continued). "In experimental asthma model, α7nAChR exerted promising effects by inhibiting NF-κB/STAT3/SOCS3 signaling." (PMID 37429998, 2024). "Both genetic and pharmacological inhibition of HDAC10 protect against airway inflammation in asthmatic mice, suggesting that the HDAC10/STAT3 axis is a potential target for treatment of asthma." (PMID 37441601, 2023). "To investigate the mechanisms by which HDAC10 regulates STAT3 in asthma, we have therefore completed a series of experiments." (PMID 37441601, 2023). "STAT3 is required for all features of asthma, including airway hyperresponsiveness and eosinophilia." (PMID 36345503, 2022). "In this study, we found that the expression of STAT3 in peripheral blood of patients with asthma was increased." (PMID 35079347, 2022). "STAT3 is a major regulator of the differentiation and function of Th17 cells, a subset of CD4+ T cells implicated in inflammation in patients with severe asthma." (PMID 35137184, 2022). "Activation of Stat3 can also promote the production of Th2 and Th17 cytokines promote inflammatory response, and aggravate asthma." (PMID 35620222, 2022). "We detected miR‐29b, B7‐H3 and STAT3 in the peripheral blood of children with asthma, explored the relationship between these molecules and their effects on T cells through in vitro cell culture, and verified it by animal model." (PMID 35079347, 2022). "Leptin impacts the pulmonary inflammation of obese asthma by activating the STAT3 signaling pathway." (PMID 36051916, 2022). "STAT3 is essential for Th2 cytokine production and Th17 lymphocyte development, and STAT3 inhibition prevents airway inflammation by blocking the accumulations of Th2 and Th17 cells in a murine asthma model." (PMID 36172200, 2022). "A more comprehensive understanding of the action mechanism of ZKPC on JAK2/STAT3 signaling pathway in human bronchial epithelial cells induced by IL-6 or M2 supernatant will enable ZKPC development in the control of asthma." (PMID 34608825, 2021). "The expression of total STAT3 was increased in both asthma models, and phosphorylated-STAT3 (p-STAT3) expression increased in the OVA + ozone group, whereas SOCS3 expression was reduced." (PMID 34760922, 2021). "Several studies have used small-molecule STAT3 inhibitors, such as STA-21/C188-9/Stattic, to suppress STAT3 signaling in different animal models of autoimmune/inflammatory diseases, such as asthma, lupus nephritis, and arthritis." (PMID 34206429, 2021). "The phosphorylated JAK2 and phosphorylated STAT3 in the cells treated with TGF-β were increased compared with the control cells, indicating the activation of JAK2/STAT3 signaling in the in vitro model of asthma." (PMID 33413331, 2021). "Inhibition of STAT3 expression by C188-9 was shown to reduce airway inflammation and airway remodeling in a house dust mite–induced asthma model created by Gavino and coworkers." (PMID 34760922, 2021). "Our study revealed that STAT3 signal mediates the function of rhynchophylline on autophagy in asthma." (PMID 33413331, 2021). "In this study, we investigated the effects of rhynchophylline on autophagy and STAT3 signal in asthma." (PMID 33413331, 2021). "The expression of IL-17A in the lung tissue of asthma patients and HCs showed a strong correlation with the expression of STAT3 and SOCS3." (PMID 34760922, 2021). "Activation of STAT3 is found in peripheral blood mononuclear cells and airway smooth muscle tissues from asthma patients and correlated with the increased cytokines." (PMID 33413331, 2021). "We also detected a positive correlation between FGFBP1 expression and p-STAT3 activity in OVA-induced asthma mouse models." (PMID 34341336, 2021). "The STAT3 pathway is reported to be activated in several immune-mediated inflammatory diseases, such as rheumatoid arthritis, lupus, asthma, and MS." (PMID 34206429, 2021). "The mice with asthma consistently exhibited higher levels of p-S6, p-STAT3, and FGFBP1 protein than in the control group." (PMID 34341336, 2021).
asthma (continued). "We discovered higher STAT3 expression and lower SOCS3 expression in the lung tissue of asthma patients compared with that of healthy controls (HCs) and observed a correlation between STAT3 expression or SOCS3 expression and the expression of IL-17A protein." (PMID 34760922, 2021). "Especially, IL-6-mediated JAK/STAT3 signaling has been proven to play crucial roles in the airway remodeling of asthma." (PMID 33374928, 2020). "Here we observed a clear phosphorylation of STAT3 in response to OVA, and ZDHXB-101 inhibited the phosphorylation of STAT3 in an OVA-induced allergy model of asthma." (PMID 31931796, 2020). "Previous reports suggested that STAT3 acts as a new allergic response epithelial regulator; therefore, recent studies support targeting this molecule as the basis for novel asthma therapy." (PMID 32512817, 2020). "The value of pSTAT3/STAT3 in general increased in the asthma model group (P < 0.05), while it reduced after the treatment of dexamethasone and Mamie cataplasm (P < 0.05, P < 0.05)." (PMID 32489402, 2020). "Asthma patients have increased STAT3 activity in airway smooth muscle cells and COPD patients have increased STAT3 levels in lung tissue compared to controls." (PMID 32509795, 2020). "Another study indicated that the activation of STAT3 was higher in mild asthma, and IL-6 stimulation increased STAT3 phosphorylation." (PMID 31924195, 2020). "Thus could confirm the strong association of JAK2, STAT3 and severe asthma." (PMID 32512817, 2020). "Those inflammatory cytokines have been importantly related to the development of asthma to up-regulate the STAT3 signals." (PMID 33374928, 2020). "STAT3 plays a vital role in lung inflammation and airway remodeling in asthma, and it has been well proved as the downstream signal of TSLP." (PMID 32117985, 2020). "Some authors have shown that STAT3 inhibition prevents lung inflammation and Th2 cell differentiation in the murine model of asthma." (PMID 31565031, 2019). "STAT3 drives the development of Th17 cells and the cytokine production by Th2 and Th17 cells, and the activation of STAT3 pathway is closely related to the development of airway inflammation, which contribute a lot to asthma." (PMID 30254626, 2018). "More recently, we demonstrated that airway inflammation and remodeling in the murine house dust mite (HDM) model of asthma is accompanied by STAT3 activation within the lung and by increased lung levels of Th2- as well as Th17-type cytokines." (PMID 30081609, 2018). "miR-19b can reduce airway remodeling, airway inflammation, and degree of oxidative stress by inhibiting STAT3 signaling through TSLP downregulation in a mouse asthma model." (PMID 30254626, 2018). "STAT3 has been demonstrated to be involved in airway inflammation, allergy, and asthma through several proposed mechanisms." (PMID 28638418, 2017). "STAT3 was recently shown to be required for the development of allergic inflammation in a mouse model of asthma." (PMID 24101903, 2013). "In a previous study of the pharmacogenetics of asthma treatment, STAT3 was one of the candidate genes that we screened for association with response to cortocosteroid treatment." (PMID 15935090, 2005). "In addition, a separate study utilizing OVA/HDM-sensitized murine asthma models demonstrated that shikonin suppresses STAT3 expression levels in the airway epithelium." (PMID 41560747, 2025). "Furthermore, it seeks to investigate the regulatory role of the JAK2/STAT3/EPAS1 axis in ferroptosis in asthma." (PMID 40165005, 2025). "Notably, these findings highlight the JAK2/STAT3/EPAS1 axis as a potential therapeutic target for asthma, offering new insights into its molecular mechanisms and identifying novel biomarkers for diagnosis and treatment." (PMID 40165005, 2025). "In addition, disruption of Th17/Treg balance caused by activation of STAT3/RORγt-STAT5/Foxp3 signaling pathway aggravated WSI-TRPM2.5 and Oe-TRPM2.5-induced asthma exacerbation further supported our conclusion." (PMID 39444792, 2024).
asthma (continued). "To explore whether shikonin alleviates asthma by regulating STAT3, we examined the activation of STAT3 and the nuclear translocation of p-STAT3." (PMID 39444792, 2024). "The JAK2/STAT3 signaling pathway in macrophages is an important target for allergic asthma development and is involved in important asthma pathological processes such as the activation of mast cells and the promotion of bronchial smooth muscle thickening and airway remodeling." (PMID 39108751, 2024). "In vitro, we analyzed whether the STAT3 activator colivelin could reverse the inhibitory effect of shikonin on asthma and detected the expression of p-STAT3 and its downstream factors." (PMID 39444792, 2024). "Mechanistically, the inhibitory effect of shikonin on asthma may be related to inhibiting the expression level of STAT3 in airway epithelium." (PMID 39444792, 2024). "In addition to IL6R, we selected STAT3 for evaluation because IL-6/signal transducer and activator of transcription 3 (STAT3)-mediated signaling involved in various pathophysiological conditions including asthma and COPD." (PMID 38302925, 2024). "By studying whether shikonin affects asthma phenotype through STAT3, it was found that shikonin can reduce the expression level of p-STAT3 and inhibit the transfer of p-STAT3 into the nucleus in asthmatic mice." (PMID 39444792, 2024). "Furthermore, in asthma and allergic inflammation, a higher STAT3 activation in Th2 cells was induced under treatment with IL-13 (León and Ballesteros-Tato, 2021)." (PMID 38044939, 2023). "Our results showed that STAT5a was decreased in the asthma model of mice, and this is supported by the another published research that the expression of STAT3 and STAT5a genes in the peripheral blood mononuclear lymphocytes were down-regulated in the severe refractory asthma." (PMID 36726128, 2023). "IL-6-mediated JAK/STAT3 signaling plays a vital role in the airway remodeling of asthma, and its inhibition prevents airway inflammation and remodeling, and blocks Th2 and Th17 cell expansion in a murine asthma model." (PMID 35222040, 2022). "Overall, these results suggested that the inhibitory effect of IL-37 on the occurrence of EMT and remodeling in asthma may be related to its regulation of IL-24 levels by influencing the activation of the p-STAT3 and p-ERK1/2 signaling pathways." (PMID 36100847, 2022). "Overall, these findings indicated that IL-37 mitigated HDM-induced airway remodeling by inhibiting IL-24-mediated EMT via the ERK1/2 and STAT3 pathways, thereby providing experimental evidence for IL-24 as a novel therapeutic target and IL-37 as a promising agent for treating severe asthma." (PMID 36100847, 2022). "STAT3 has been reported to be involved in macrophage polarization and may be involved in the immune response of asthma." (PMID 35079347, 2022). "After the addition of STAT3 antibody in the co‐culture system of macrophages and naive T cells, the differentiation of Th2 cells decreased and the secretion of IL‐4 also decreased, which indicated that STAT3 may also involved in the immune mechanism of asthma." (PMID 35079347, 2022). "The expression of SOCS3 and STAT3 has been evaluated in airway inflammation in some animal models, but we are the first to observe their changes in the lung tissue of asthma patients." (PMID 34760922, 2021). "In this study, we revealed that rhynchophylline suppressed autophagy of ASMCs through inhibiting the JAK2/STAT3 signaling pathway, which may contribute to its therapeutic action on asthma." (PMID 33413331, 2021). "Thus, it is likely that activated STAT3 is involved in asthma, at least partly, by regulating transcriptional activation of FGFBP1." (PMID 34341336, 2021). "Simultaneously, SHE further suppressed the Th17 cell response by reducing the mRNA expression of RAR-related orphan receptor gamma (RORγT) and phosphorylation of signal transducer and activator of transcription 3 (STAT3), which create the primary neutrophils for asthma." (PMID 34070821, 2021).
asthma (continued). "The suppressive effect of AG on JAK1/STAT3 signaling pathway by regulating Th17 cells may have the potential for treating asthma or other inflammation-mediated diseases." (PMID 34194525, 2021). "STAT3 signal is usually activated in asthma and plays an important role in disease process." (PMID 33413331, 2021). "Furthermore, rhynchophylline suppressed the JAK2/STAT3 signaling pathway, which was activated in asthma." (PMID 33413331, 2021). "Growing evidence reveals that STAT3 plays a crucial role in asthma." (PMID 33413331, 2021). "STAT3 expression is correlated with mucus secretion as well as inflammation, responsiveness, and remodeling of the airways, which suggests an important role of STAT3 in asthma pathogenesis." (PMID 34760922, 2021). "In the current study, based on the analysis of human airway epithelial cells and OVA-induced asthma mouse models, we demonstrated that STAT3 serves as a downstream effector of mTORC1 and transcriptionally upregulates FGFBP1 through directly binding to its promoter and enhancing its transcription." (PMID 34341336, 2021). "Both genes have a high correlation with asthma pathogenicity (>3.5 p-value (−log10)), where JAK2 and STAT3 were linked to moderate and severe asthma phenotypes and have a high number of pathogenic SNPs (8 and 24 SNPs, respectively) and related human diseases (18 and 37 diseases, respectively)." (PMID 32512817, 2020). "STAT3 was been shown earlier to regulate the allergic response in asthma." (PMID 31931796, 2020). "Peppermint oil would help to alleviate asthma by inhibiting the IL-6/JAK2/STAT3 pathway." (PMID 33374928, 2020). "Collectively, MEO may have an inhibitory effect on asthma under the condition of PM10 exposure through the IL-6/JAK2/STAT3 signaling pathway." (PMID 33374928, 2020). "Whether miR-223 modulates STAT-3 in asthma and COPD and whether it is involved in neutrophilic or eosinophilic responses remains to be determined." (PMID 32509795, 2020). "Furthermore, Th2-specific IL-4 and IL-13 cytokines were produced by bronchial epithelial cells via STAT3-dependent allergic inflammation in asthma." (PMID 33374928, 2020). "These genes may explain certain features of asthma severity, including allergic response (STAT3) and inflammation in asthmatic airways (NR3C1 and COL1A1)." (PMID 32512817, 2020). "Since glucocorticoids are known to have numerous side effects and after chronic administration patients can become refractory, novel asthma therapeutics to induce SP-D may seek to directly activate STAT3 signaling." (PMID 31572383, 2019). "Our study found no appreciable association between STAT3 gene expression and either mild asthma or SRA." (PMID 28638418, 2017). "On the other hand, many studies signify the STAT3 role in pathogenesis of asthma and SRA." (PMID 28638418, 2017). "STAT3 has been shown earlier to regulate allergic response in asthma." (PMID 24499258, 2013). "Furthermore, we demonstrated that signaling pathway of Stat3 mediated TSLP-induced airway remodeling in asthma." (PMID 24167583, 2013). "Signal transducer and activator of transcription 3 is a transcription factor latent in the cytoplasm; the gene (STAT3) is activated by a wide range of cytokines, and may play a role in lung development and asthma pathogenesis." (PMID 15935090, 2005). "However, limited studies have investigated the function of STAT3 in Res-mediated asthma treatment." (PMID 40453664, 2025). "However, whether p-PKM2 plays a role in asthma is unclear, and whether shikonin reduces p-STAT3’s abundance in airway epithelial cells through p-PKM2 needs further investigation, which will be the direction of our future research." (PMID 39444792, 2024). "Importantly, targeting STAT3 for the treatment of asthma has achieved certain research findings." (PMID 39444792, 2024).
asthma (continued). "In addition, MLE-12 cells were given 25 μg/mL colivelin (a STAT3 activator) in the presence of shikonin to observe whether activation of STAT3 could reverse the inhibitory effect of shikonin on asthma." (PMID 39444792, 2024). "Additionally, several animal studies revealed that rosmarinic acid has anti-inflammatory activity through the inhibition of NF-κB and STAT3 signaling pathways and may be applied against arthritis, inflammatory bowel disease, and asthma." (PMID 35337106, 2022). "Hence, STAT3 may be involved in the hypersecretion, remodeling, and hyperresponsiveness of airways observed in asthma." (PMID 34760922, 2021). "We hypothesized that JAK2/STAT3 signal may mediate the effect of rhynchophylline on asthma." (PMID 33413331, 2021). "Therefore, STAT3 activated after phosphorylation may have an important role in T2-low asthma and be involved in the development of corticosteroid resistance." (PMID 34760922, 2021). "Moreover, STAT3 has been considered the potential target for asthma therapy." (PMID 34194525, 2021). "However, whether STAT3 signaling pathway could mediate the function of rhynchophylline on asthma remains unclear." (PMID 33413331, 2021). "Therefore, the activation of STAT3 in asthma may induce chronic inflammation and airway remodeling via promoting lung fibroblast senescence." (PMID 32117985, 2020). "Furthermore, a single nucleotide polymorphism (SNP) of STAT3 has been associated with atopic -but not with non-atopic asthma- in children." (PMID 32509795, 2020). "Moreover, there is an investigation to find the effects of PM2.5 on JAK2/STAT3 signaling pathway in human bronchial epithelial cells, giving the possibility of a therapeutic target for asthma by inhibiting the JAK/STAT signaling pathway under an air pollution-exposed condition." (PMID 33374928, 2020). "However, there are also several studies that discount a role for STAT3 in asthma." (PMID 28638418, 2017). "Furthermore, it has been proposed that STAT3 is a potential target for asthma and SRA therapeutics." (PMID 28638418, 2017). "Our results indicate that genetic variants in STAT3, independent of asthma treatment, are determinants of FEV1 in both adults and children with asthma, and suggest that STAT3 may participate in inflammatory pathways that have an impact on level of lung function." (PMID 15935090, 2005). "Our investigation also identified important genes involved in ferroptosis and asthma, including EPAS1, STAT3, G6PD, CYBB, and CBS." (PMID 40165005, 2025). "This study aims to better understand how the JAK2/STAT3/EPAS1 axis regulates inflammation and ferroptosis in asthma." (PMID 40165005, 2025). "Previous studies have shown that miR‐140‐3p can modulate the JAK2/STAT3 signaling by targeting HMGB1, reducing airway inflammation and remodeling in asthma." (PMID 40044625, 2025). "The protein expression levels of TGF-β1, p-STAT3, and CTGF in the lung tissue of mice in the asthma + CUR-NPs group (CUR equivalent: 25 mg/kg) were significantly lower compared to those in the asthma model group (p < 0.05)." (PMID 38708080, 2024). "Direct targeting of the 3’UTR region of STAT3 by exosome miR-301a-3p reduced the release of inflammatory cytokines TNF-α, IL-1β, and IL-6, which can inhibit OVA-induced asthma." (PMID 39444792, 2024). "The administration of IL-27 via intranasal route has been shown to mitigate Th2-mediated allergic lung inflammation and restructuring in murine asthma models through the restoration of both STAT1 and STAT3 signaling pathways." (PMID 39062111, 2024).